STAT3 (signal transducer and activator of transcription 3)
Diseases named in the same sentence as STAT3 in open-access papers (continued):
Sharing a sentence is not in itself a finding about the gene and the disease.
cancer (continued). "Inhibition of STAT3 signaling has been shown to inhibit cancer cell growth and induce apoptosis indicating STAT3 is a promising therapeutic target for cancer." (PMID 31361777, 2019). "Accumulating studies have indicated that the signal transducer and activator of transcription 3 (STAT3) protein can be employed as a putative target for cancer therapy." (PMID 31878046, 2019). "Autocrine IL-6/STAT3 signaling fuels CAFs proliferation and stimulates the horizontal transfer of miR-221/222high microvescicles to cancer cells." (PMID 30927908, 2019). "The importance of the JAK/STAT3 pathway in tumorigenesis and progression of cancer has been emphasized." (PMID 31477564, 2019). "IL-11 and LIF also contribute to cancer progression by driving EMT through STAT3 and Akt/mTOR signaling, thereby conferring an enhanced migratory capacity." (PMID 31684144, 2019). "Following transformation, persistent STAT3 activation drives the emergence of mesenchymal/cancer-stem cell (CSC) properties, important determinants of metastatic potential and therapy failure." (PMID 31684144, 2019). "Various attempts have been made to develop agents that prevent STAT3 phosphorylation and/or dimerization and act as anti-cancer agent." (PMID 31383893, 2019). "STAT3 mediated transcriptional activation of hTERT led to self-renewal genes turn-on, hence increased the stemness in cancer cells." (PMID 31360301, 2019). "Meanwhile, IL-6 contributed to cancer chemoresistance by gp130/MAPK/STAT3 mediated activation of transcription factors C/EBPβ/δ, epithelial to mesenchymal transition, overexpression of p-glycoprotein and expansion of cancer stem cells." (PMID 30897064, 2019). "Taking everything into account, in respect to the ability of PLGA NPs in delivery, anti-STAT3-loaded PLGA NPs can be considered as promising agents in cancer immunotherapy by targeting DCs." (PMID 31569687, 2019). "A more recent study shows that in PDA, CAFs induce an invasive EMT and proliferative phenotype of cancer cells through the activation of STAT3 in a co‐culture system." (PMID 31609088, 2019). "EOC cells cultured under hypoxic conditions revealed higher levels of pY-STAT3 (Tyr705); however, with knockdown of STAT3 expression, the proliferation rate of cancer cells was significantly reduced." (PMID 31861720, 2019). "Identification of novel small-molecule STAT3 inhibitors from natural products will be of great interests in the development of novel anti-cancer therapeutics targeting HCC CSCs." (PMID 30709346, 2019). "Metformin treatment-associated ‘AMPK independent’ anti-cancer effects are mediated by regulated in DNA Damage-1 (REDD1; also known as DNA damage inducible transcript-4-DDIT4), Rag GTPases, and signal transducer and activator of transcription-3 (STAT3)." (PMID 31835318, 2019). "Attenuation of the STAT3 signalling pathway resensitised resistant cancer cells to chemotherapeutic agents as well as inhibited cancer growth." (PMID 31406162, 2019). "In our unpublished research, we examined the culture supernatant of ADSCs using a Multiplex analysis, and IL-1/6 were present at extremely high levels, and the STAT3 signalling pathway was activated in cancer cells, which were treated with ADSC CM." (PMID 31781249, 2019). "In cancer, increased IL-6 levels result in hyperactivation of JAK/STAT3 signaling, typically associated with poorer prognosis." (PMID 31399589, 2019). "We further observed that ODZ10117 effectively inhibited the level of tyrosine phosphorylated STAT3 in various cancer cell lines that are persistently activated or activated by IL-6-stimulation." (PMID 31684051, 2019). "Previous studies have reported that IL-6 or IL-6 downstream signaling confers chemotherapeutic resistance by triggering the PI3K/Akt, MAPK/ERK, or Jak1/STAT3 signaling pathway in cancer cells." (PMID 30927911, 2019). "STAT3 is involved in cancer in multiple ways, as detailed in several reviews and articles of this Special Issue of Cancers." (PMID 31752278, 2019).
cancer (continued). "Following 24 h of treatment, A009 was able to reduce IL-6 and STAT3 phosphorylation (Ser727) in DU-145, showing a potential cancer-preventive role by blocking IL-6/STAT3 signaling in vitro." (PMID 30646518, 2019). "Although encouraging results have been shown in various cancer types, clinical trials on STAT3-targeted therapies in HCC are still limited." (PMID 31731457, 2019). "Girdin expression and Stat3 activation act as a positive feedback loop in the invasion of cancer cells." (PMID 30769863, 2019). "Per the immunoprecipitation assay (IP), ITGA2 interacted with STAT3 in various types of cancer cells." (PMID 31818309, 2019). "After assessing the efficacy of PTPRD knockdown by shRNA, we determined that stable knockdown of PTPRD increased cellular proliferation, as well as cancer cell migration and invasion, most likely via STAT3, as previously reported." (PMID 31805999, 2019). "Calon and colleagues have demonstrated for the first time that TGFβ released by colon cancer cells activates STAT3 pathway in stromal cells, which in turn enhance their secretion of IL-11 that increase the metastatic potential of cancer cells." (PMID 30927908, 2019). "Given the emerging role of STAT3 in canine cancers such as osteosarcoma, there is interest in combining JAK/STAT inhibition (oclacitinib) with conventional chemotherapy." (PMID 31409327, 2019). "The transcription factor Signal Transducer and Activator of Transcription 3 (STAT3) shows low or null activity in normal unstimulated cells but an enhanced activity in various types of human cancer cells." (PMID 30622697, 2019). "Activation of Janus activated kinase 2 (JAK2)/signal transducer and activation of transcription-3 (STAT3) pathway is involved in cancer progression through the enhancement of cell proliferation, differentiation, and angiogenesis." (PMID 31766284, 2019). "It has been reported that disruption of constitutively activated STAT3 can promote cell apoptosis, and the STAT3-signaling pathway has become an attractive key target for cancer therapy." (PMID 31816985, 2019). "Activated Stat3 dimerizes and induces gene expression of a variety of genes, many of which are known to be important for hallmarks of cancers like migration/invasion (Mmp2, Mmp9;) or EMT-like features and immune evasion/suppression (e.g., Snai1;)." (PMID 30857197, 2019). "The suppression of phosphorylated STAT3 (p-STAT3) can induce apoptosis and inhibit metastasis in cancer." (PMID 31186039, 2019). "STAT3 belongs to the signal transducer and activator of transcription family, and phosphorylated STAT3 is involved in cancer proliferation, invasion, and metastasis through its modulation of the transcription of genes related to cell survival." (PMID 31406162, 2019). "They revealed that Napabucasin efficiently suppressed metastasis and relapse of a variety of cancers by inhibition of STAT3-driven gene transcription." (PMID 31277685, 2019). "Some reports showed that cancer cell growth was inhibited after the interruption of c-Myc and STAT3 dimerization by small molecules." (PMID 31601833, 2019). "We further proved that miR-665 was the target of BCAR4 and subsequently activated signal transducers and STAT3 signaling which is an important pathway in cancer stem cells self-renewal." (PMID 30962766, 2019). "Specifically, upon interleukin (IL)-6 receptor activation, STAT3 is phosphorylated and enhances cancer cell growth, survival, and immune evasion." (PMID 31470515, 2019). "Nevertheless, it must be emphasized that current clinical studies of STAT3-targeted agents have been chiefly based on cancer types other than HCC and more efforts to evaluate their clinical performance in HCC are strongly urged." (PMID 31731457, 2019). "STAT3 regulates a diverse repertoire of cellular responses and plays an important role in immunity to both cancer and infection." (PMID 31552035, 2019).
cancer (continued). "The JAK2/STAT3 is one that has drawn many researchers’ attention, since it mediates angiogenesis in both cancer cells and MDSCs." (PMID 31847487, 2019). "Furthermore, STAT3 upregulation may be associated with drug resistance in cancer treatment." (PMID 31406162, 2019). "Contrastingly, multiple de novo somatic GOF mutations arise in STAT3 and STAT5B leading to cancer pathogenesis, and such mutations have been implicated in both solid and liquid tumors." (PMID 31717342, 2019). "IL6, secreted by TAMs, binds to the IL6 receptor (IL6R) on the cancer cell surface to phosphorylate STAT3 (pSTAT3)." (PMID 30927925, 2019). "It is well recognized that signal transducer and activator of transcription 3 (STAT3) and Src are implicated in the promotion of cellular motility and invasion critical for cancer metastasis." (PMID 31067694, 2019). "We have identified that inhibition of the TGFβ‐IL‐6 paracrine signaling axis reduces STAT3 activation in cancer cells and also blunts immune evasion." (PMID 31609088, 2019). "The transcription factor STAT3 is aberrantly activated in many types of cancer, and this hyperactivation is usually associated with a poor clinical prognosis." (PMID 31817106, 2019). "We uncover that STAT3 activation is detected in cancer cells and cells of the microenvironment, particularly in basal-type UBC." (PMID 31438567, 2019). "There is considerable direct evidence suggesting the crucial role of STAT3 in various processes, including cancer growth, invasion, and apoptosis, and it can be activated by various proto-oncogenes and oncogenes." (PMID 31221094, 2019). "It is a first-in-class cancer stemness inhibitor that inhibits transcription of STAT3 downstream target genes." (PMID 31731457, 2019). "The critical role that overexpression and/or hyperactivation of STAT3 plays in the development of multiple cancers has spawned considerable effort to develop inhibitory molecules with potential for clinical application." (PMID 31671769, 2019). "This suggested that MET and STAT3 are important oncogenes in LINC00857 regulating cancer progression in EAC cells." (PMID 31085800, 2019). "As an oncogene, STAT3 is constitutively activated, which largely leads to chemoresistance and promotes migration and invasion in a variety of cancer cells." (PMID 31244991, 2019). "Napabucasin (NAPA) is an inhibitor of cancer stemness and STAT3 pathways, which lead to cancer stem cell viability." (PMID 30863442, 2019). "Based on these results, we suggest that Src/Stat3/S100A7 signaling contributes to the metastasis of cancer cells through the EMT pathway." (PMID 31731716, 2019). "Napabucasin (BBI608) is a newly developed small molecule inhibitor of STAT3, which has been shown to impair self-renewal and induce apoptosis in cancer stem cells of colorectal, pancreatic, non-small cell lung, gastric, and prostate cancers." (PMID 31277685, 2019). "In the present study, we performed two-track screening assays in combination with structure-based computational database screening and cell-based high-throughput screening to identify small-molecule inhibitors for STAT3-targeted cancer therapy." (PMID 31684051, 2019). "The transcription factors NF-κB and Stat3 are activated in many cancers and play an essential role in CSC formation." (PMID 31658701, 2019). "STAT3 signalling is well known to be activated in cancer and is specifically involved in EMT, in the acquisition of a stem-cell-like phenotype and in defining the premetastatic niche." (PMID 30947697, 2019). "Persistent activation of STAT3 contributes to uncontrolled cell proliferation, angiogenesis, apoptotic resistance, and prosurvival effect in cancer cells." (PMID 31847229, 2019). "In this context, SLs are promising compounds in cancer drug discovery and their anti-STAT3 activity as well as their ability to disrupt redox homeostasis place them as lead compounds in the development of innovative therapies." (PMID 31781335, 2019).
cancer (continued). "EGFR was reported to be the upstream regulator critical for STAT3 phosphorylation in cancer cells and cancer stem- like cells." (PMID 30713819, 2019). "The central involvement of STAT3/5 in cancer has made these molecules attractive targets for small-molecule drug development, but currently there are no direct STAT3/5 inhibitors of clinical grade available." (PMID 31817042, 2019). "This suggests that the direct effect of IL‐6 on cancer cells via STAT3 activation is important during the progression of TGFβR2‐mutant tumors." (PMID 31609088, 2019). "Collectively, these pieces of evidence suggest, STAT3 as one of the major contributing factors in the initiation and progression of cancer and blockade of STAT3 signaling can be a suitable therapeutic approach to treat human cancers." (PMID 31575007, 2019). "We also predict that the use of these NP can significantly lower the unwanted side effects of STAT3 inhibitors, as they are targeted to cancer cells, and preferentially released inside of these cells." (PMID 30791634, 2019). "HNF4α is a TF that takes part in two distinct feedback loops that occur in normal and cancer cells, respectively, consisting of IL-6R; the miRNAs miR-24, miR-124, and miR-629; and STAT3." (PMID 31557902, 2019). "The STAT3 signaling is frequently activated through the binding of cytokines and growth factors to their corresponding receptors in cancer cells." (PMID 31088482, 2019). "This proof-of-concept study thus supports the notion that highly therapy-resistant cancers such as malignant gliomas and hard-to-drug genes like Stat3 can be efficiently targeted using siRNA in vivo." (PMID 30857197, 2019). "Small molecule inhibitors have demonstrated a role for STAT3 in the regulation of muscle mass during cancer cachexia." (PMID 30918582, 2019). "A majority of cancers are associated with constitutive activation of members of the STAT family, particularly STAT3." (PMID 31007650, 2019). "Signal transducer and activator of transcription 3 (STAT3) is commonly hyperactive in many cancers and is associated with cancer cell proliferation, invasion, migration, and angiogenesis." (PMID 30863721, 2019). "The JAK2-modulated transcription factor STAT3, involved in immune responses, inflammatory processes, and cancer initiation, is activated by several cytokines, growth factors, and oncogenes." (PMID 31492006, 2019). "This is mainly due to the ability to generate potent, specific STAT3 inhibitors and the number of cancers in which aberrant STAT3 signalling is a major driver of malignancy." (PMID 31817106, 2019). "Pathways relating to cellular immunity also observed in SKOV3, OVCAR3, and OVCAR8 STAT3 KO cells were enriched in four cancer types: interferon gamma response, immune response, immune cell activation and differentiation." (PMID 31534498, 2019). "STAT3 phosphorylation, nuclear localization, and target gene expression are activated in cancer cachexia." (PMID 31456341, 2019). "We will discuss options for targeting STAT3/5 in cancer, either directly or indirectly through the inhibition of upstream kinases, receptors and/or ligands." (PMID 31684144, 2019). "Aberrant JAK-STAT signaling (specifically STAT3) is common in various cancer due to their constitutive activation in response to stimulators e.g. cytokines, growth factors, receptors (TLRs/GPCRs), polypeptide ligands and miRNAs38." (PMID 31601896, 2019). "Recent studies found the JAK2/STAT3 pathway to be another candidate for pharmaceutical agents to limit muscle wasting in experimental cancer cachexia." (PMID 31285507, 2019). "It should be restated that resistance to STAT3 blockade in many cancer types can be acquired by MEK activation, suggesting combined STAT3/MEK inhibition." (PMID 31438567, 2019). "It has been shown to effectively induce apoptosis, suppress growth and downregulate STAT3 target genes in in vitro and in vivo cancer models, including liver, lung, head and neck and ovarian cancer." (PMID 31731457, 2019).
cancer (continued). "Though some cancer cells inevitably spread to the liver, simultaneous inhibition of STAT3-p-Y705 significantly decreases the adherence of cell-matrix, and ultimately reduces the liver metastasis in CRC." (PMID 31506552, 2019). "In doing so, xanthatin preferentially inhibited the growth of cancer cell lines that have constitutively activated STAT3 and p65." (PMID 30993883, 2019). "The JAK2/STAT3 signaling mediates the effects of many growth factors and cytokines, and has been intensely investigated in many cancer types." (PMID 30782177, 2019). "For example, lipophilic antipsychotic drugs and others that can inhibit the major mechanism of resistance of the target therapy, such as PI3K-AKT-mTOR and STAT3, can be tested with a wide range of target therapies and cancers." (PMID 31480389, 2019). "Despite the importance of STAT3 as an oncogenic driver in many cancers, targeting STAT3 therapeutically has been challenging." (PMID 31817106, 2019). "This study showed that BP-1-102 markedly increased the protein levels of p-MEK and p-ERK in KRAS mutant cancer cells, suggesting that STAT3 inhibitor can result in MEK and ERK up-regulation." (PMID 31484165, 2019). "Increasing studies have shown that the overexpression of STAT3 enhances cell proliferation and metastasis in a variety of cancers." (PMID 31486564, 2019). "STAT3 controls the expression of genes that contribute to the hallmarks of cancer, including proliferation, survival, angiogenesis, immune evasion and inflammation." (PMID 31817106, 2019). "STAT3 has been recognized as an attractive therapeutic target in oncology for the development of inhibitors and several agents have been identified to interfere with STAT3 signaling in various cancer models." (PMID 31575007, 2019). "Effects of apigenin on JAK2/STAT3 pathway and cytotoxicity in cancer cells were mediated by its docking to 26S proteasome in cancer cells." (PMID 31100782, 2019). "In view of its significance in cancer biology, STAT3 has been postulated to be an attractive anti-cancer target, and many STAT3 inhibitors (such as Stattic, S3I-201, and S3I-1757) have been developed." (PMID 30791634, 2019). "Dysregulated STAT3 activity is involved in hematologic malignancies, head and neck cancers, and leukemia and has been implicated in the pathogenesis of a subset of solid tumors." (PMID 32257917, 2019). "STAT3, activated by tyrosine phosphorylation in response to growth factors and cytokines, was mainly involved in the oncogenesis of several human cancers, including GC." (PMID 30944204, 2019). "STAT3 is a transcription factor whose activation contributes to many cancer functions including survival, proliferation, inflammation, angiogenesis, invasion, and metastasis and is regarded as an oncogene." (PMID 31565097, 2019). "In line with the idea that CCL18 is a stimulator of PKCδ signaling, our data demonstrated that blocking CCL18 signaling suppressed the expression of the PKCδ downstream factors STAT3 or NF-κB as well as various cancer-related factors." (PMID 31126309, 2019). "Although various aspects of STAT3 signaling have been reported in several cancer models, the precise molecular mechanisms and consequences of inhibiting STAT3 are not fully understood in EOC." (PMID 31534498, 2019). "Apart from phosphorylation and methylation, other post-translational modifications like acetylation, SUMOylation, S-nitrosylation and ubiquitination are reported to regulate the functions of STAT3 in multiple cancer types." (PMID 31130718, 2019). "Persistent STAT3 activation has been identified to be a prominent feature in many cancers of epithelial origins." (PMID 30736824, 2019). "Among the seven STAT family members, STAT3 is reported most frequently to participate in the regulation of a wide range of cancers including colon, lung, breast, ovarian, and prostate." (PMID 31841120, 2019).